CLEC3A (C-type lectin domain family 3 member A)
Description:
Promotes cell adhesion to laminin-332 and fibronectin.
Synonyms: CLECSF1
Tractability: Antibody: UniProt places it where antibodies can reach, with high confidence; UniProt predicts a signal peptide or a membrane-spanning region; its Gene Ontology location is reachable by antibodies, with medium confidence.
Gene: Protein-coding gene on chromosome 16 (78,022,515 to 78,066,761, forward strand). Ensembl gene ENSG00000166509.
Subcellular location: Secreted
Subcellular location (Human Protein Atlas): Endoplasmic reticulum; Predicted to be secreted
Gene Ontology:
Molecular function: carbohydrate binding
Biological process: ossification; skeletal system development
Cellular component: extracellular region
Genetic constraint (gnomAD): Loss-of-function variants: 28 observed, 21.99 expected, observed/expected ratio (o/e) 1.27, 90% interval 0.94 to 1.73. The upper end of that interval is the gene's LOEUF score, 1.73, which puts it in group 6 of 6, group 1 being the genes least tolerant of losing a copy. Missense variants: 357 observed, 252.25 expected, observed/expected ratio (o/e) 1.42, 90% interval 1.3 to 1.54. Synonymous variants: 110 observed, 93.27 expected, observed/expected ratio (o/e) 1.18, 90% interval 1.01 to 1.38.
Homologues: Orthologues: chimpanzee CLEC3A (99% identical), macaque CLEC3A (94% identical), dog CLEC3A (90% identical), rabbit CLEC3A (89% identical), guinea pig CLEC3A (88% identical), mouse Clec3a (87% identical), pig CLEC3A (87% identical), rat Clec3a (86% identical), tropical clawed frog clec3a (67% identical), zebrafish CLEC3A (55% identical). Paralogues in human: CLEC3B (46% identical), CLEC11A (31% identical).
Diseases named in the same sentence as CLEC3A in open-access papers:
CLEC3A is named in the same sentence as 17 diseases in open-access papers, as found by Europe PMC text mining. Sharing a sentence is not in itself a finding about the gene and the disease. The quoted sentences say what the papers report.
breast carcinoma (7 papers, 2019 to 2023). "TNBC with increased SD on PrecontrastT1 showed a 23-fold, 13-fold, sevenfold, fivefold, and fivefold upregulation of CLEC3A, SRGN, HSPG2, KMT2D, and VMP1 respectively, and these genes are associated with poor survival in breast cancer." (PMID 37391754, 2023). "Our results are further supported by the fact that CLEC3A is a promising treatment target for breast cancer." (PMID 35692369, 2022). "The expression profile of CLEC3A, as a useful benchmark described in this study, supports the clinical utility of this biomarker in the diagnosis of metastatic SLNs in breast carcinoma, but more encouraging results merit further investigation." (PMID 31983196, 2020). "We applied an absolute quantitative real-time RT-PCR to quantitate the expression of CK19, KLK11, and CLEC3A mRNAs in 79 FFPE SLNs from 35 breast cancer patients." (PMID 31983196, 2020). "In summary, although very limited study has been conducted on the expression levels of KLK11 and CLEC3A mRNAs in the SLN tissue in breast cancer, we observed the overexpression of these genes in the positive SLN tissue similar to the CK19 biomarker." (PMID 31983196, 2020). "Among these SeCEP genes, CLEC3A is a C-type lectin that promotes tumor adhesion in breast cancer and was recently found to enhance plasminogen activation by tissue-type plasminogen activator." (PMID 31146747, 2019). "A previous study indicated that CLEC3A promotes invasion and metastasis of breast cancer cells by activating the PI3K/Akt signaling pathway." (PMID 31129920, 2019). "CLEC3A, a C-type lectin domain family 3 member A, has been reported in human breast cancer." (PMID 35692369, 2022). "Our study constructed the prognostic signature based on breast cancer PD-1/PD-L1 pathway molecular typing-related genes (IFNG, JCHAIN, ELOVL2, PIGR, PAGE5, ACTL8, and CLEC3A)." (PMID 37154982, 2023).
breast invasive ductal carcinoma (1 paper, 2023). "Patients with breast invasive ductal carcinoma with high CLEC3A expression were associated with higher lymph node metastasis and poor overall survival." (PMID 37154982, 2023).
colon cancer (1 paper, 2020). "CLEC3A is specifically expressed in the cartilage, and a significant expression in the breast and colon cancer tissue has been identified." (PMID 31983196, 2020).
lung squamous cell carcinoma (1 paper, 2024). "Among them, CLEC3A was highly expressed in patients with estrogen-positive breast cancer, the expression of CLEC3A is significantly associated with the overall survival of patients, and other studies found that CLEC3A was associated with immune invasion of lung squamous cell carcinoma." (PMID 39493752, 2024).
osteoporosis (1 paper, 2024). A condition of reduced bone mass, with decreased cortical thickness and a decrease in the number and size of the trabeculae of cancellous bone (but normal chemical composition), resulting in increased fracture incidence. "In contrast, cg18243574 (CLEC3A) had lower expression in osteoporosis CIS2." (PMID 38472169, 2024).
osteosarcoma (1 paper, 2024). A usually aggressive malignant bone-forming mesenchymal neoplasm, predominantly affecting adolescents and young adults. "cg18243574 is a site within CLEC3A, and this gene is a member of the C-type lectin superfamily and a candidate oncogene in osteosarcoma, whose suppression might inhibit osteosarcoma cell proliferation and promote chemosensitivity." (PMID 38472169, 2024).
tumor (8 papers, 2016 to 2022). "For example, the upregulated CLEC3A has been shown highly expressed on the tumor cell surface, and the cleavage of CLEC3A by MMP7 was reported to weaken tumor cell adhesion and migration." (PMID 32539762, 2020). "CLEC3A had the highest frequency in tumor samples; its overexpression promotes tumor progression and poor prognosis in breast invasive ductal cancer (IDC) and is related to higher lymph node and poorer overall survival (OS) of breast IDC." (PMID 31850079, 2019). "It is reported that CLEC3A expression is markedly higher in breast invasive ductal cancer tissues, and elevated CLEC3A expression may be correlated with breast invasive ductal cancer metastatic potential." (PMID 35692369, 2022). "A recent study using RNA sequencing and immunohistochemistry revealed an overexpression of C-type lectin domain family 3 member A (CLEC3A), matrix metallopeptidase 7 (MMP7) and lipocalin 2 (LCN2) in recurrent PanNETs compared to non-recurrent tumor." (PMID 36551599, 2022).
cancer (3 papers, 2019 to 2025). A tumor composed of atypical neoplastic, often pleomorphic cells that invade other tissues. "Meanwhile, there are no clear patterns for some genes within each cluster, such as CLEC3A and H2AFJ, partly reflecting the spatial heterogeneity of cancers." (PMID 39954675, 2025).
infection (1 paper, 2025). The state of being infected such as from the introduction of a foreign agent such as serum, vaccine, antigenic substance or organism. "This study evaluates the in vivo antimicrobial activity of CLEC3A-derived peptides using a mouse model of biomaterial-associated infection." (PMID 40006601, 2025). "The aim of this study was to evaluate the effectiveness of CLEC3A-derived peptides HT-47 and WRK-30 in reducing bacterial adhesion and mitigating infection in vivo in a murine biomaterial-associated infection model." (PMID 40006601, 2025). "In conclusion, CLEC3A-derived peptides HT-47 and WRK-30 retain their antimicrobial activity in vivo in a murine biomaterial-associated infection model." (PMID 40006601, 2025).
CLEC3A also shares sentences with these, for which no sentence is quoted: breast (1 paper); breast tumor (1); lung carcinoma (1); lymph node metastasis (1); osteoarthritis (1); pancreatic neuroendocrine tumor (1); septic arthritis (1); triple-negative breast carcinoma (1).